DBP (D-box binding PAR bZIP transcription factor)
Diseases named in the same sentence as DBP in open-access papers (continued):
Sharing a sentence is not in itself a finding about the gene and the disease.
bronchiectasis (1 paper, 2021). Segmental, irreversible dilation of the bronchial tree resulting in the accumulation of secretions which leads to obstruction. "We evaluated the possible clinical impact of DBP polymorphisms and isoforms in an observational, cross-sectional study conducted in 116 bronchiectasis patients, who were genetically characterized for rs4588 and rs7041 SNPs." (PMID 34829802, 2021). "For these reasons, the aim of this work was to evaluate the impact of DBP polymorphisms and isoforms on bronchiectasis patients’ characteristics." (PMID 34829802, 2021).
chronic hepatitis (1 paper, 2022). An active inflammatory process affecting the liver for more than six months. "It was also found that LD for DBP-rs4588-DBP-rs7041, indicating non-random association or co-segregation of these SNPs, was also observed in a series with chronic hepatitis, as well as in Brazilian women with polycystic ovary syndrome." (PMID 35919232, 2022).
coronary artery disease (1 paper, 2016). "The aim of the study was to assess the effect of vitamin D-binding protein (DBP) polymorphism on coronary artery disease (CAD)." (PMID 27143969, 2016).
cystinosis (1 paper, 2023). Cystinosis is a metabolic disease characterized by an accumulation of cystine inside the lysosomes, causing damage in different organs and tissues, particularly in the kidneys and eyes. "In this study, we used a ctns−/−[Tg(l-fabp:DBP:eGFP)] fish model for cystinosis that shows a 15% reduction (mean) in green fluorescence at 5 days post-fertilization as compared with the ctns+/+[Tg(l-fabp:DBP:eGFP)] larvae, indicative of an increase in DBP-GFP protein loss in the fish water." (PMID 38016974, 2023).
fibrosarcoma (1 paper, 2022). A malignant mesenchymal fibroblastic neoplasm affecting the soft tissue and bone. "The opposing functions of DBP and E2F8 as enhancer and repressor respectively, in Th9 cells contribute to Th9-medaited anti-tumor effects in experimental models of melanoma and fibrosarcoma and suggest their biological significance in cancer immunotherapy." (PMID 36241625, 2022).
gangliosidosis (1 paper, 2020). A group of autosomal recessive lysosomal storage disorders marked by the accumulation of gangliosides. "Diagnoses included nonketotic hyperclycinemia (NKH) (n = 2), ornithine transcarbamylase deficiency (OTC) (n = 3), propionic academia (n = 1), congenital disorder of glycosylation 1a (CDG1a) (n = 1), D‐bifunctional protein deficiency (DBP) (n = 1), and GM1 Gangliosidosis (n = 1)." (PMID 32495504, 2020).
glioma (1 paper, 2022). A benign or malignant brain and spinal cord tumor that arises from glial cells (astrocytes, oligodendrocytes, ependymal cells). "WGCNA was performed to identify the genes that were coexpressed with the four key CCGs (ARNTL, NPAS2, CRY2, and DBP) in glioma." (PMID 35832846, 2022). "Key CCGs, including ARNTL, NPAS2, CRY2, and DBP, acted as potent diagnosis and prognosis biomarkers of glioma patients and rhythmically regulated cancer-related signaling pathways and coexpressed genes to affect drug sensitivity and possible clinic outcomes." (PMID 35832846, 2022). "Four CCGs (ARNTL, NPAS2, CRY2, and DBP) with rhythmic expression were not only identified as differentially expressed genes but also had significant independent prognostic ability in the overall survival of glioma patients and were highly correlated with glioma prognosis in COX analysis." (PMID 35832846, 2022). "The differential expression of CCGs in glioma grading confirmed that cluster I genes (ARNRL, NPAS2, and TIMELESS) and CRY1, with cluster II genes (CRY2, DBP, NR1D1, NR1D2, PER2, PER3, and RORA) showed significantly opposite expression trends in brain tissues." (PMID 35832846, 2022). "Besides, the expression of eight CCGs (CRY2, DBP, NR1D1, NR1D2, PER2, PER3, RORA, and TIMELESS) was negatively regulated by methylation and positively regulated by CNV in glioma, which is consisting with previous studies that DNA methylation and CNV can promote abnormal gene expression." (PMID 35832846, 2022).
Graves disease (1 paper, 2024). Graves' disease is an autoimmune disorder that leads to overactivity of the thyroid gland (hyperthyroidism).It is caused by an abnormal immune system response that causes the thyroid gland to produce too much thyroid hormones. "In a Polish population study, a significant association between Graves’ disease and the Lys allele at codon 420 of DBP was discovered." (PMID 38892458, 2024).
hip fracture (1 paper, 2018). Traumatic or pathological injury to the hip in which the continuity of either the femoral head, femoral neck, intertrochanteric or subtrochanteric regions is broken. "Significantly lower concentrations of all 25OHD fractions and binding proteins (DBP, albumin) as well as Ca, but not albumin corrected Ca, were observed in patients with hip fracture as compared to the control group." (PMID 30071650, 2018).
Hypercholesterolemia (1 paper, 2018). An increased concentration of cholesterol in the blood. "In our previous study, suppressing the feeding rhythm induced hypercholesterolemia by advancing the phase of CYP7A1 by altering the circadian oscillation of DBP in rats." (PMID 30379940, 2018).
Impaired glucose tolerance (1 paper, 2018). An abnormal resistance to glucose, i.e., a reduction in the ability to maintain glucose levels in the blood stream within normal limits following oral or intravenous administration of glucose. "Other genetic factors, such as genetic polymorphisms of vitamin D-binding protein (DBP) or vitamin D receptor (VDR), may affect vitamin D status and may play a role in impaired glucose tolerance or T2DM." (PMID 29743959, 2018).
kidney cancer (1 paper, 2021). Primary or metastatic malignant neoplasm involving the kidney. "Five rhythmic genes, including PER2, DBP, PER3, CRY2, and RORA, have significant prognostic role in patient survival in at least two types of kidney cancer." (PMID 34977153, 2021).
kidney damage (1 paper, 2023). "It is reported that proteinuria had a great impact on the concentration of vitamin D, which may be due to the loss of vitamin D-binding protein (DBP) caused by kidney damage in SLE." (PMID 37681199, 2023).
liver cirrhosis (1 paper, 2023). "It is noteworthy that, VDR rs3782905 CC and DBP rs7041 TG genotypes are more associated with a higher risk of HCV-induced liver cirrhosis than with HCC progression in HCV-infected patients." (PMID 38066559, 2023). "It is noteworthy that, VDR rs3782905 CC and DBP rs7041 TG genotypes are higher in HCV induced liver cirrhosis than with HCC progression in HCV infected patients." (PMID 38066559, 2023). "As a result, this study aims to determine the significance of the VDRs (rs2228570, rs3782905, rs11568820) and DBP (rs7041) for the susceptibility to HCC in Egyptian patients with chronic HCV infection and their effect on the progression of liver cirrhosis to carcinogenesis." (PMID 38066559, 2023). "This study aims to determine the significance of the VDRs (rs2228570, rs3782905, rs11568820) and DBP (rs7041) for the susceptibility to HCC in Egyptian patients with chronic HCV infection and their effect on the progression of liver cirrhosis to carcinogenesis." (PMID 38066559, 2023).
liver fibrosis (1 paper, 2022). "Our results revealed that the transcripts of DBP and GAS6 were upregulated in liver of HFD-fed mice, confirming that liver fibrosis and NASH might be developed." (PMID 35743193, 2022).
malaria (1 paper, 2023). Malaria is a serious and sometimes fatal disease caused by a parasite that commonly infects a certain type of mosquito which feeds on humans. "The zoonotic malaria parasite, P. knowlesi, has larger invasive merozoites and contains a smaller, less redundant, DBP and RBL repertoire than P. falciparum." (PMID 37528099, 2023).
nephrotic syndrome (1 paper, 2021). A collection of symptoms that include severe edema, proteinuria, and hypoalbuminemia; it is indicative of renal dysfunction. "Moreover, Vitamin D major carrier, the D-binding protein (DBP), is less represented due to Nephrotic Syndrome (NS), proteinuria, and the alteration of the cubilin–megalin–amnionless receptor complex in the renal proximal tubule." (PMID 33671780, 2021).
neuroblastoma (1 paper, 2021). Neuroblastoma (NB) is the most common solid, extracranial childhood tumor. "In our study, we observed downregulation of DBP and upregulation of EGR1 in U2OS cells, which is consistent with previous observations that were carried out using patient-derived lymphoblastoid cells and human neuroblastoma cells." (PMID 34905700, 2021).
papillary thyroid cancer (1 paper, 2021). "When downregulation of the DBP gene in papillary thyroid cancer (PTC) cell lines was observed, tumor proliferation and migration were enhanced." (PMID 33868582, 2021).
peroxisomal biogenesis disorders (1 paper, 2012). "There are other peroxisomal disorders that present with MRI abnormalities resembling X-ALD, in particular peroxisomal biogenesis disorders and ACOX1 or DBP deficiency with late onset of symptom." (PMID 22889154, 2012).
prostate tumor (1 paper, 2010). "Finally, DBP-maf was shown to cause a reduction in urokinase plasminogen activator receptor (uPAR) expression in prostate tumor cells." (PMID 20976141, 2010). "In this study we show for the first time that DBP-maf exhibits a direct and potent effect on prostate tumor cells in the absence of macrophages." (PMID 20976141, 2010).
septic shock (1 paper, 2021). Shock caused by infection; frequently caused by gram negative bacteria, although some cases have been caused by other bacteria, viruses, fungi, and protozoa; characterized by fever, chills, tachycardia, tachypnea, and hypotension. "While CRY1, NR1D1, NR1D2, DBP, PER2 were suppressed in septic shock patients, CRY2, surprisingly was significantly upregulated compared to healthy young men." (PMID 33900485, 2021). "In addition, the expression of the clock genes CRY1, NR1D1, NR1D2, DBP, and PER2 were suppressed in septic shock patients, whereas CRY2 was significantly upregulated compared to healthy young men." (PMID 33900485, 2021).
Shock (1 paper, 2021). The state in which profound and widespread reduction of effective tissue perfusion leads first to reversible, and then if prolonged, to irreversible cellular injury. "Additionally, we found that NR1D1, NR1D2, CRY1, CRY2, PER1, PER2 and DBP had altered rhythms in at least some patients with septic shock." (PMID 33900485, 2021).
Stroke (1 paper, 2024). Sudden impairment of blood flow to a part of the brain due to occlusion or rupture of an artery to the brain. "Of these, 20 associations were found for AF (in 6 loci with 17 genes), 22 for DBP (6 loci with 16 genes), 3 for stroke (1 locus with 3 genes) and 8 for cIMT (3 loci with 6 genes)." (PMID 39537608, 2024).
thyroid autoimmunity (1 paper, 2015). "Recently, several genetic studies have demonstrated an association between thyroid autoimmunity susceptibility and gene polymorphisms of numerous proteins and enzymes that are associated with vitD functions, including VDR, DBP, CYP27B1, and CYP2R1." (PMID 26681939, 2015).
infection (39 papers, 2006 to 2026). The state of being infected such as from the introduction of a foreign agent such as serum, vaccine, antigenic substance or organism. "At the late stage of infection when virion assembly takes place, the large majority of early-replicated vDNA loses protein IVa2 as well as DBP while gaining an association with 33K suggesting that this pool of vDNA is no longer engaged in replication." (PMID 39454009, 2024). "To confirm loss of E4orf6/DBP expression, we performed time-course infections in A549 cells using WT Ad5, the E4orf6/7;E4orf6/DBP double KO (ΔSS), and the previously used dl355 ΔE4orf6 viruses." (PMID 36095031, 2022). "Our findings demonstrate that DBP regulates a key step at the onset of the late phase of infection and that this activity is unambiguously linked to the formation and integrity of viral RCs." (PMID 35254132, 2022). "These included a reduction in E3-19K at each time point examined, a reduced level of E4orf6 expression at 24 hours post-infection and a delay in expression of the E2-encoded DBP." (PMID 27137912, 2016). "We next asked what effect the loss of E4orf6/DBP might have on viral replication during multiple cycles of infection." (PMID 36095031, 2022). "In addition, infection with dl356 (which lacks E4orf6/7) and dl1002 (which lacks both E4orf6 and 6/7, but retains E4orf6/DBP due to the mutation being downstream of the splice donor) both retain prominent staining of RSA3 at VRCs." (PMID 36095031, 2022). "Additionally, in infected cells, RIα appeared to overlap with the HAdV-5 encoded DNA-binding protein (DBP), suggesting possible co-localization with viral replication centres during infection." (PMID 27137912, 2016). "To ascertain whether the loss of E4orf6/DBP affected genome replication, we infected A549 cells with WT Ad5 or the ΔSS virus, and isolated genomic DNA to perform quantitative PCR over a time-course of infection." (PMID 36095031, 2022). "A consistent feature of FACT inhibition, however, was a significant reduction in the protein levels of DBP, which correlated positively with a significant reduction in the formation of VRCs during infection, and the production of new, infectious virus." (PMID 42187241, 2026). "We immunostained for HA to visualize protein VII localization, DBP to visualize infection progression, and DAPI." (PMID 39745448, 2025). "Protein levels of E1A and DBP sustained higher expression late in infection, whereas dl309-infected samples showed greater reduction late in infection." (PMID 41186411, 2025). "Lastly, we chose the E2A-encoded DBP for development of the fluorescence VRC reporter virus, as DBP is expressed during the early phase of infection, is regulated by E1A, and is commonly used to demark VRCs." (PMID 38639487, 2024). "In the early phases of infection, replication of Ad DNA takes place within nuclear foci containing DBP, a viral single-stranded DNA-binding protein." (PMID 39162498, 2024). "Dual-color pulse-chase experiments combining IEDDA-VdU with CuAAC revealed that the early-replicated vDNA along with host DNA was compacted and, upon prolonged infection, became devoid of detectable active Pol II transcription and DBP-positive marks." (PMID 39454009, 2024). "In the late phases of infection (24 to 36 h post-infection), ViPR bodies are observed as large nuclear foci containing DNA and surrounded by DBP-positive ring-like structures." (PMID 39162498, 2024). "Combined immunoprecipitation/immunoblotting experiments show that DBP specifically interacts with USP7 in WT H5pg4100-infected H1299 cells upon USP7 overexpression or with endogenous USP7 in infection experiments of HCT116 cells." (PMID 35254132, 2022). "The three transcripts displaying this pattern, including E4-promoter driven DBP and frameshifted E4-Unk, are all much more abundant during the late phase of infection even though canonical E4 transcripts are expressed early." (PMID 36095031, 2022).
infection (continued). "Using this orthogonal system, we corroborated our finding that E4orf6/DBP co-localized with VRCs, whereas E4orf6 remained broadly nucleoplasmic upon infection." (PMID 36095031, 2022). "The HAdV serotype 5 (HAdV-C5) DBP is a 529-amino-acid product of the E2A gene and is expressed early and late in infection, regulated by different promoters (20, 23, –, 25)." (PMID 35254132, 2022). "At 12 hours post-infection (hpi) the majority of viral transcripts detected were early RNAs, particularly E1A-large and E1A-small, E1B-19K and E1B-55K, early promoter DBP, E3-12K, E3-19K, and E4orf3." (PMID 36095031, 2022). "While flag-E4orf6/DBP was recruited to USP7-marked VRCs during infection, flag-E4orf6 remained markedly diffuse throughout the nucleus." (PMID 36095031, 2022). "Our results unequivocally demonstrate that RC formation is dependent on DBP and, remarkably, essential for progression into the late phase of infection, which is followed by viral progeny production." (PMID 35254132, 2022). "Upon infection of A549 cells with WT Ad5 we saw that E4orf6 had reached maximal expression as early as 16 hpi, whereas E4orf6/DBP was first detected at 24 hpi and reached maximal expression at 48 hpi." (PMID 36095031, 2022). "Now that we know a major fraction of the E4orf6 signal detected at late times of infection by RSA3 or M45 immunoblot is actually E4orf6/DBP, we revisited this subcellular localization determined by immunofluorescence." (PMID 36095031, 2022). "At 16 hpi, when DBP was mostly organized in spheroid foci, the RF was almost 100%, and decreased at later times post-infection when more complex ring-like, fiber-like or amorphous structures were observed." (PMID 34578359, 2021). "SMC6 exhibits diffuse nuclear and occasional perinuclear localizations during mock or Ad5 WT infection but exhibits striking reorganization to colocalize with DBP and BrdU at VRCs during AdΔE4 infection." (PMID 34463575, 2021). "The time-course analysis of transcription revealed that 17-AAG inhibits the expression of the HAdV-5 early genes E1A and DBP at the time of infection, but it seems to be relatively ineffective when applied later." (PMID 33670684, 2021). "As expected, at 16 hpi, all DBP-assemblies were small structures with a spheroid shape, and at later times post-infection, DBP-positive structures increased in size and deviated from a spherical shape (20–36 hpi and 1E)." (PMID 34578359, 2021). "For this step, we mined 19 experimental RNA expression datasets, representing 15 unique DBP deletion strains as well as numerous host infection-mimicking conditions including nutrient limitation, metal ion limitation, and low pH." (PMID 34327153, 2021). "Serological studies have shown that region II of PvDBP, which P. vivax uses to bind to human erythrocytes, induces antibodies against DBP and is naturally immunogenic in people residing in endemic regions, through repeated exposure to the infection." (PMID 33374596, 2020). "To be able to correlate the steady state mRNA levels with protein levels, we performed western blotting for E1A, DBP, and viral structural proteins at 6, 12, 18, 24, and 36 hours after infection." (PMID 30677073, 2019). "Levels of DBP mRNA were highly variable and we observed very low levels at 16 and 24 h after infection for all of the mutants, while dl309-infected cells showed robust mRNA and protein levels at 24 h." (PMID 29257057, 2017). "There was a striking reduction in the number of replication foci observed 24 hours after infection with virus that lacks protein VII where very few DBP-positive cells were evident even at high multiplicity of infection." (PMID 28628648, 2017). "Western blot analysis showed that the viral-early E2A DBP and E1B-55k proteins were expressed at 12 h post-infection (h p.i.), while the viral-late protein VI (pVI) was produced at 18 h p.i.." (PMID 28631589, 2017).